HP (haptoglobin)
Diseases named in the same sentence as HP in open-access papers (continued):
Sharing a sentence is not in itself a finding about the gene and the disease.
mastitis (continued). "The results of other studies support this study that high concentrations of haptoglobin in serum or milk occur when animals suffer from mastitis." (PMID 33665459, 2021). "A significant increase of haptoglobin concentrations in cow milk occurred only hours after experimental induction of mastitis." (PMID 33665459, 2021). "It has been reported that the concentrations of SAA and HP were higher in the serum and milk of mastitis cows than in healthy cows." (PMID 34941838, 2021). "In breast milk, haptoglobin levels have been proposed as a biomarker of subclinical mastitis in dairy cows." (PMID 32824434, 2020). "Diagnostic results for cows with and without mastitis at all sampling points including California mastitis test, rectal temperature, serum β-hydroxybutyrate, serum haptoglobin levels, and latent classes." (PMID 33195534, 2020). "Haptoglobin also serves as biomarker for inflammatory processes such as subclinical mastitis, which results in elevated milk SCC." (PMID 32705016, 2020). "Genes coding for proteins such as haptoglobin, cathelicidin antimicrobial peptide, and lingual antimicrobial peptide have been identified as potential biomarkers for mastitis detection." (PMID 31921295, 2019). "Other proteins of interest were S100 proteins and acute phase proteins, including haptoglobin, also in view of the previous results generated by proteomic studies carried out on milk from sheep and cows with mastitis." (PMID 31676851, 2019). "Acute phase proteins (APPs) including haptoglobin (Hp), CRP and mammary associated serum amyloid A3 (M-SAA3) are also used as biomarkers for diagnosing bovine mastitis." (PMID 31288621, 2019). "At present, attention is being focused on using acute phase proteins such as haptoglobin, serum amyloid A., as biomarkers for the diagnosis of mastitis." (PMID 29470489, 2018). "During inflammatory episodes such as mastitis, plasma concentrations of acute phase proteins such as haptoglobin and ceruloplasmin are likely to increase." (PMID 28740504, 2017). "At acute clinical mastitis in dairy cows, the haptoglobin concentration increases markedly both in blood and milk." (PMID 26202328, 2015). "Haptoglobin has been used as a biomarker of mastitis, metritis, and several inflammatory conditions and bacterial infections in dairy cows." (PMID 26479383, 2015). "Two proteins FGG and HP upregulated by 16.75- and 5.45- fold in mastitis-infected cow’s tissues were involved in S. aureus infection pathway." (PMID 25273983, 2014). "The results of this study are therefore consistent with previous research and lend further support for the use of haptoglobin as a potential biomarker of bovine mastitis." (PMID 23776543, 2013). "In past decades, haptoglobin has been shown to be a useful biomarker for monitoring the occurrence and severity of inflammatory responses in cattle with mastitis, pneumonia, enteritis, peritonitis, endocarditis, abscesses, endometritis and hoof disease." (PMID 23418487, 2013). "In addition, 9 cows presented both high haptoglobin and ketosis, 4 presented both ketosis and mastitis, 2 presented both mastitis and high haptoglobin, and 1 cow exhibited all three conditions." (PMID 41527118, 2026). "Similarly, haptoglobin and apolipoprotein A-I have been recognized as key biomarkers of clinical mastitis, a critical disease affecting animal health and milk production." (PMID 40646845, 2025). "The presence of the acute phase protein haptoglobin in blood and milk has been frequently associated with different pathologies in cows, such as mastitis, with the haptoglobin considered as a non-specific marker of stress, inflammation, or disease." (PMID 36770644, 2023). "First, although haptoglobin concentrations increase in mastitis milk, it presents a wide range (from 2.08 to 55.46 μg/mL) when the SCC is above 200 × 103 cells/mL, which may overlap with the concentrations of healthy and sub-clinical mastitis cows." (PMID 36009897, 2022).
mastitis (continued). "Milk haptoglobin can be a potential target for an early detection of mastitis in goats." (PMID 33665459, 2021). "These indicate that milk haptoglobin is a potential target of early diagnosis of mastitis in cows." (PMID 33665459, 2021). "The purposes of our study were to investigate the presence of haptoglobin in the somatic cells of goat milk, the expression of mRNA of haptoglobin in the somatic cells, and to develop an indirect ELISA against haptoglobin for the early detection of mastitis in Peranakan Ettawa (PE) goats." (PMID 33665459, 2021). "These resulting in a higher concentration of goat milk haptoglobin in animals with severe mastitis." (PMID 33665459, 2021). "New mastitis biomarkers under development are the levels of chaperonins for pathogen recognition, prostaglandin D synthase, serotransferrin, bovine serum albumin, various caseins, cytochrome C oxidase, annexin V, haptoglobin and many more." (PMID 34361932, 2021). "In light of this, the finding of such high amounts in the mastitic udder might appear a bit unusual, although coherent with the numerous reports of haptoglobin increase in serum in presence of mastitis." (PMID 26088507, 2015). "Significant positive correlations were identified between clinical mastitis incidence on the week of sampling and levels of serum haptoglobin, and between the % CD335+ cells within the PBMC population and the number of lameness episodes within a lactation period." (PMID 23776543, 2013). "Although, High HP levels have been reported in the blood of cattle with infections/diseases like mastitis, metritis, traumatic reticulitis, bacterial nephritis and bovine respiratory syncytial virus and many others, there is no literature indicating its involvement in BVDV infection." (PMID 20946620, 2010). "Therefore, it is possible that among the herd there would have been animals in an initial phase of the development of mastitis as a result of transmissibility between animals that were sharing facilities and generating a concentration of haptoglobin in the tank." (PMID 36770644, 2023). "These sensitive indicators include cytokines and acute phase protein measurements, particularly haptoglobin, fibrinogen, and amyloid A which could be determined in cow serum and/or milk, and in the future may become useful in early mastitis diagnostics as well as a preventive tool." (PMID 36899749, 2023). "The β-chain haptoglobin could be a potential biomarker for mastitis diagnosis." (PMID 33665459, 2021). "Haptoglobin concentrations increase to sixfold in dairy cows with infectious and metabolic diseases at slaughter compared to animals with minor lesions, In cattle, haptoglobin is effective in the diagnosis and prognosis of mastitis, enteritis, peritonitis, pneumonia, endocarditis, and endometritis." (PMID 26202328, 2015). "Examples of such enzymes are NAGase, serum amyloid A (SAA), haptoglobin (Hp), lactate dehydrogenase (LDH), and plasminogen, which can serve as biomarkers for mastitis." (PMID 39335280, 2024). "For example, cow 1 had a claw lesion that resulted in an increase in haptoglobin between 75 and 96 DIM, cow 3 developed mastitis directly after calving, and cow 7 suffered from a puerperal infection." (PMID 35681803, 2022). "However, this condition may not compromise the use of haptoglobin as the diagnostic marker because the aim of the study was to detect a lower concentration of haptoglobin as the indicator of acute mastitis." (PMID 33665459, 2021). "Previously it has been reported that haptoglobin levels in milk and serum correspond with SCC, which support its use as a biomarker for mastitis detection." (PMID 32071371, 2020). "Haptoglobin, SAA, and c-reactive protein (CRP) have been identified in milk, indicating their potential as biomarkers of mastitis." (PMID 32867136, 2020).
mastitis (continued). "In cows with experimentally induced mastitis (using specific microbes, such as Staphylococcus uberis), the level of M-SAA3 in milk reached a peak at 6 h, and haptoglobin reached a peak at 10 h after infection." (PMID 31750312, 2019). "Haptoglobin and SAA are synthesized in the bovine mammary epithelium, and the substantial increase in their secretion into milk was observed during mastitis." (PMID 31750312, 2019). "Haptoglobin concentrations measured during the trial were on average below a critical value of 250–10,000 mg·L−1, normally observed during SARA, clinical mastitis or experimentally induced aseptic inflammation." (PMID 31137610, 2019). "Acute phase proteins haptoglobin (Hp), serum amyloid A (SAA) and lipopolysaccharide binding protein (LBP) have suggested to be suitable inflammatory markers for bovine mastitis." (PMID 18554387, 2008). "Mastitis, both experimentally induced and field cases, resulted in significant changes in serum and milk amyloid A and HP, and Gram-negative bacteria appeared to produce a higher APP response than Gram-positive bacteria, with few exceptions." (PMID 39237955, 2024). "In cattle, the most important APPs are haptoglobin (Hp), serum amyloid A (SAA) and α1-acid-glycoprotein (AGP), which levels are used as biomarkers of various pathological conditions and as predictive values for mastitis, respiratory diseases, and lameness." (PMID 35012560, 2022). "Studies on mastitis in dairy cows have shown that haptoglobin is detected not only in blood but also in milk." (PMID 33665459, 2021). "However, she was retained in the mastitis group because at enrollment she had a swollen udder, serous discharge, strong positive CMT, and a 5-fold elevation in haptoglobin level (82.6 μg/mL) compared to the healthy cows (mean 16.0 ± 4.2 μg/mL)." (PMID 33195534, 2020). "Genes coding for proteins such as Haptoglobin (HP), Serum Amyloid A (SAA), Cathelicidin antimicrobial peptide (CAMP), and Lingual antimicrobial peptide (LAP) have been identified as potential biomarkers for mastitis detection." (PMID 29470489, 2018). "A number of significant correlations were found between immune traits and other recorded traits including: CD4+:CD8+ T lymphocyte ratio and subclinical mastitis; % CD8+ lymphocytes and fertility; % CD335+ natural killer cells and lameness episodes; and serum haptoglobin levels and clinical mastitis." (PMID 23776543, 2013). "Haptoglobin (Hp) and serum amyloid A (SAA) are acute phase proteins that increase during infection and inflammation and may serve as biomarkers for detecting subclinical mastitis and assessing its impact on calf health." (PMID 40963590, 2025). "Milk whey fraction and serum obtained from animals with or without clinical mastitis in Puducherry, India, were subjected to SDS-PAGE followed by western blot and immuno-detection of haptoglobin protein." (PMID 29056737, 2016).
Sepsis (46 papers, 2009 to 2026). Sepsis is defined as life-threatening organ dysfunction caused by a dysregulated host response to infection. "After comprehensive adjustment for potential confounders, the inverse association remained stable, establishing haptoglobin as an independent protective factor against AKI in sepsis." (PMID 40743649, 2025). "This association remained statistically significant after adjusting for potential confounders in the multivariate analysis, with higher serum haptoglobin levels associated with a reduced risk of AKI in sepsis patients." (PMID 40743649, 2025). "This phenomenon can also be observed in the present study, where early lower levels of haptoglobin in sepsis patients were associated with a higher incidence of AKI." (PMID 40743649, 2025). "In conclusion, the present study demonstrates that elevated early haptoglobin levels in sepsis patients are independently linked to a lower risk of AKI." (PMID 40743649, 2025). "In sepsis, the body’s triggered inflammatory response against the underlying infection leads to elevated haptoglobin levels as part of the acute-phase reactants." (PMID 39710434, 2024). "ARG1 and HP play different but complementary roles in the pathophysiology of SAP- associated sepsis." (PMID 39364223, 2024). "Our study revealed that HP was upregulated in sepsis samples and demonstrated good diagnostic value, making it an ideal biomarker for sepsis." (PMID 38227599, 2024). "In summary, HP is up-regulated in sepsis with a strong diagnostic value, and it can serve as a reliable biomarker for sepsis diagnosis." (PMID 38227599, 2024). "In conclusion, HP is identified as a potential diagnostic indicator for sepsis patients, and HP promotes neutrophil inflammatory activation by regulating PFKFB2 in the glycolytic metabolism of sepsis confirmed by in vitro experiments." (PMID 38227599, 2024). "Kelly and coworkers reported an association of elevated haptoglobin plasma levels in critically ill patients with sepsis with a decreased risk of in-hospital mortality." (PMID 31964768, 2020). "Major adverse kidney events, a complication common to severe sepsis, have been associated with haptoglobin levels below the detection limit of typical measurements in burn patients." (PMID 31568522, 2019). "Reduced plasma levels of hemopexin and haptoglobin (Hp) also correlated with an increased risk for mortality in septicemia." (PMID 24691127, 2014). "Past human studies of haptoglobin and hemopexin have focused on their properties as acute-phase reactants and as a response to the underlying inflammation associated with sepsis." (PMID 24225252, 2013). "In this cohort study of critically ill patients with sepsis, there was a significant association between plasma levels of haptoglobin and in-hospital mortality." (PMID 24225252, 2013). "•Increased plasma levels of haptoglobin and hemopexin measured early in sepsis are associated with decreased in-hospital mortality." (PMID 24225252, 2013). "In critically ill patients with sepsis, elevated plasma levels of haptoglobin were associated with a decreased risk of in-hospital mortality and this association was independent of confounders." (PMID 24225252, 2013). "In critically ill patients with sepsis, increased plasma haptoglobin and hemopexin levels were associated with a reduction in in-hospital mortality." (PMID 24225252, 2013). "•Identified an inverse association between serum haptoglobin levels and sepsis-associated AKI risk." (PMID 40743649, 2025). "Furthermore, retrospective data in humans suggest that increased plasma-free hemoglobin is associated with worse mortality in sepsis, and that septic survivors have higher haptoglobin levels than those who die." (PMID 37407986, 2023). "In combination with HP expression, leukocyte levels may help stratify the patients’ risk for development of sepsis at any time point during the course after trauma." (PMID 26607226, 2015).
Sepsis (continued). "Haptoglobin, due to its ability to quickly capture and bind free hemoglobin, may mitigate the renal injury caused by oxidative stress and inflammatory responses associated with free hemoglobin during sepsis." (PMID 40743649, 2025). "Intriguingly increased plasma levels of haptoglobin measured early in sepsis are associated with decreased in-hospital mortality so the differential appearance of this gene may also be specific to particular subsets of patients and timing, stressing the importance of metadata associations." (PMID 37304268, 2023). "In this subgroup, the risk to develop secondary sepsis could further be assessed by HP expression." (PMID 26607226, 2015). "We conducted a retrospective cohort study to test the hypothesis that higher plasma concentrations of haptoglobin and hemopexin in adults with sepsis are associated with a decreased risk of in-hospital mortality, independent of severity of illness and cell-free hemoglobin levels." (PMID 24225252, 2013). "Specifically, it is unknown whether haptoglobin and hemopexin levels are only a marker of illness or if elevations in sepsis have a protective function and are associated with improved outcomes independent of severity of illness and cell-free hemoglobin levels." (PMID 24225252, 2013). "More clinical studies are needed to clarify the appropriate range of haptoglobin levels in sepsis patients to provide a reference for treatment." (PMID 40743649, 2025). "The authors sought to determine the optimal range of haptoglobin levels early in septic patients and explore its potential as a therapeutic target for improving sepsis outcomes." (PMID 40743649, 2025). "Currently, the mechanisms by which haptoglobin reduces AKI in sepsis patients are not well understood." (PMID 40743649, 2025). "Previous studies have demonstrated a relationship between haptoglobin and hemopexin concentrations and clinical outcomes in patients with sepsis." (PMID 40429487, 2025). "The results demonstrated a significant increase in the expression of HP in sepsis patients compared to normal samples (Student’s T-Test, P-value = 1.97e-02)." (PMID 39710434, 2024). "Given the pro-inflammatory effect of HP, our research reveals that HP-regulated PFKFB3-mediated glycolytic reprogramming is a possible sepsis treatment target." (PMID 38227599, 2024). "The high expression of HP in monocyte of sepsis was further validated using fluorescence-activated cell sorting (FACS)." (PMID 39710434, 2024). "Based on the ROC curves, HP was considered the hub gene in sepsis, and its expression difference in sepsis and control groups was substantially significant." (PMID 38227599, 2024). "Administration of exogenous haptoglobin improves survival in a canine model of sepsis, and there is some retrospective data suggesting that exogenous haptoglobin administration reduces acute kidney injury (AKI) in humans undergoing cardiac surgery." (PMID 37407986, 2023). "Sepsis is known to increase plasma-free hemoglobin, a source of oxidative stress that can potentially be mitigated by haptoglobin." (PMID 37407986, 2023). "One day after sepsis induction, all animals presented peritonitis with bacterial infection as well as elevated C-reactive protein, haptoglobin, IL-1Ra, IL-6, and IL-1b." (PMID 38087374, 2023). "Clinical data have shown an association between increased plasma levels of CFH, decreased concentrations of haptoglobin and mortality for patients with sepsis." (PMID 35193645, 2022). "Another study discovered that haptoglobin also bound HMGB1 through a CD163-dependent pathway that confers protection against HMGB1-mediated inflammation in sepsis." (PMID 36230933, 2022). "For example, a study on the temporal profile of renal proteome changes induced by sepsis highlighted that ceruloplasmin (CR) and haptoglobin (Hp) are upregulated 90 minutes after the onset of sepsis." (PMID 33425215, 2020).